TNF (tumor necrosis factor)
Diseases named in the same sentence as TNF in open-access papers (continued):
Sharing a sentence is not in itself a finding about the gene and the disease.
melanoma (continued). "Stimulation with TNF-α significantly increased both melanoma cell migration at 24 h (+21%) and invasion through fibronectin (+35%) but did not upregulate/activate the expression of latent MMP-2 constitutively produced by these cells and did not upregulate their general protease activity." (PMID 12966436, 2003). "In this study, we focused on the question of whether TNF-α was promoting melanoma invasion through fibronectin via upregulation of proteolytic enzymes." (PMID 12966436, 2003). "The enhancement of BCNU cytotoxicity by TNF may be important if it can be translated into patients with melanoma." (PMID 2245169, 1990). "Therefore, one of our objectives was to investigate the potential relationship established between IL-6 and/or TNF-α and the white-blood-cell-based inflammatory indices, which could provide valuable information about the efficacy of melanoma treatment." (PMID 40564098, 2025). "Thus, GCS may represent a valuable target in melanoma to prevent TNF-induced immune escape and progression." (PMID 39136013, 2024). "Additionally, TNF has been identified as a potent regulator of sphingolipid metabolism, which could contribute to melanoma aggressiveness and the process of melanoma dedifferentiation." (PMID 39136013, 2024). "Furthermore, based on our new findings, it suggests that RIPK4 may play a pivotal role in regulating the expression of IL-8 and IL-6 in response to TNF-α stimulation of melanoma cells." (PMID 38656555, 2024). "Therefore, apart from the regulation by NF-κB downstream of IRE1α, the expression and secretion of IL-6 and TNF-α might also be directly transcriptionally regulated by XBP1 downstream of IRE1α in melanoma undergoing ER stress." (PMID 38291473, 2024). "Therefore, we evaluated TNF-α levels in the serum of patients with advanced melanoma." (PMID 38656555, 2024). "To better describe TNF-induced dedifferentiation, we merged the different gene signatures that were positively correlated, based on hierarchical clustering, and generated three features to describe the differentiated, transitory and dedifferentiated melanoma states." (PMID 39136013, 2024). "Interestingly, accumulating evidence suggests that TNF may play a role in melanoma progression and resistance to immunotherapies." (PMID 39136013, 2024). "Recent research indicates that in melanoma driven by B-type Raf kinase (BRAF) mutations, resistance to inhibitors of the mitogen-activated protein kinases (MAPK) pathway may arise through macrophage-secreted Tumor Necrosis Factor alpha (TNF-α)." (PMID 38835380, 2024). "Melanoma exosomes have been shown to induce a spectrum of macrophage phenotypes secreting a variety of anti-inflammatory (IL-4, IL-10, IL-11, and IL-13) but also pro-inflammatory (TNF-α, IL-12B, IL-1β, IL-6, iNOS, and CCL22) factors, reflecting the spectrum of phenotypes detected in the TME." (PMID 38533720, 2024). "The establishment of this mechanism by TNF could contribute to the aggressiveness of melanoma." (PMID 39136013, 2024). "Therefore, we questioned whether melanoma cells could become the dominant source of TNF-α in the skin or whether indirect activation of KCs in tumor-bearing skin, for example, via melanoma IL-1β, would also contribute to TNF-α–dependent migration of LCs." (PMID 37043573, 2023). "Furthermore, in combination with the hypoglycemic agent metformin, a drug largely used for type 2 diabetes, the EGCG inhibited the NF-kB/STAT3 signaling pathways, resulting in reduced melanoma growth and metastatic potential, and decreased pro-inflammatory mediators such as IL-6, IL-10 and TNF-α." (PMID 36768978, 2023). "Moreover, human ILC2s have been shown to be able to respond to melanoma cells in vitro by up-regulating TNFα and IL-13; thus, it is possible that cell-to-cell interactions may contribute to activation." (PMID 36765891, 2023). "It implies that ZBSO may suppress melanoma independently of TNF-α and IL-1β pathways." (PMID 37081962, 2023).
melanoma (continued). "Interestingly, we found a correlation between increased levels of IL-6, IL-8, TNF-α and the accumulation of circulating PMN-MDSC in metastatic but not in non-metastatic patients, underlining their role in the melanoma progression." (PMID 36860876, 2023). "Therefore, to determine the cellular mechanisms by which this may occur and further characterize the relationship between melanoma and epidermal LCs, we developed an integrated executable model based on melanoma-derived TNF-α." (PMID 37043573, 2023). "Interestingly, in preclinical models of mouse melanoma, anti-TNFα antibodies increased CD8 tumor-infiltrating lymphocytes, which might suggest a favorable prognosis." (PMID 36981837, 2023). "In addition, after being co-cultured with NK-92 EVs, the melanoma cells exhibited low cell viability but high cell apoptosis in a does dependent manner, which might be mediated by the secretion of TNF-α from NK-92 EVs." (PMID 37575250, 2023). "And the negative correlation between 6 ICD-related genes (CD8A, PRF1, IFNG, CXCR3, TNF, CD8B) and risk score and the protective function of these 6 genes in SKCM indicates that drugs targeting these genes may be a novel treatment method in melanoma." (PMID 36211436, 2022). "Interestingly, NFATC2 (nuclear factor of activated T-cells), a transcriptional regulator of TNF and TNF receptor expression in melanoma cell lines is also overexpressed in the chordoma samples and may be targeted by the downregulated miRNA miR-665." (PMID 36033338, 2022). "Notably, NF-κB also exerts pleiotropic proliferative effects in malignant melanoma, and we recently reported that ONC elicited the inhibition of NF-κB DNA-binding through the downregulation of its target gene tumor necrosis factor (TNF)α in the human A375 melanoma cell line." (PMID 35742999, 2022). "Thus, the prognosis of melanoma might be improved by increasing the TNF-α levels through reducing anxiety with psychiatric intervention, along with surgical and systemic treatments." (PMID 36405903, 2022). "Thus, our study demonstrates that the regulation of LUBAC-mediated M1-ubiquitination of RIPK1 and c-FLIPL by PP6 can serve as a checkpoint for TNFα-mediated cell death, which may provide a potential mechanism for promoting melanoma progression." (PMID 36071040, 2022). "However, clinical studies performed in the 1990s showed that locoregional administration of a high doses of TNF combined with chemotherapy, by isolated limb perfusion, can induce high response rates in subjects with sarcomas of the extremities or with melanomas." (PMID 35890309, 2022). "Anti-tumor necrosis factor (TNF) biologics such as infliximab, adalimumab, and certolizumab, are generally well-tolerated, however; they are expensive and may increase the risk of infections as well as melanoma skin cancer." (PMID 35783604, 2022). "Both tumor-infiltrating TGF-β+ (78.6%) and TNF-α+ (87.0%) B cells were predominantly of the class-switched memory phenotype, supporting the notion that memory B cells may be a key source of cytokine expression in melanoma lesions." (PMID 35909944, 2022). "All 40 melanoma cell lines in our panel responded to 1000 U/mL TNFα with diminished IκB protein accumulation, and although the degree of IκB reduction was variable (one to six-fold reduction in the presence of TNFα), all 40 melanoma cell lines showed reduced IκB accumulation." (PMID 34073253, 2021). "We next examined whether TNFα promoted melanoma state-specific changes." (PMID 34073253, 2021). "Hence, we eagerly await the results from the first Phase Ib, open-label trial that is evaluating the administration of nivolumab (anti-PD-1) and ipilimumab (anti-CTLA-4) in combination with the anti-TNFα drug infliximab or certolizumab in patients with advanced melanoma." (PMID 34445397, 2021).
melanoma (continued). "We have previously shown that a cytokine cocktail consisting of IL‐1β, TNFα, IFNγ, IFNα, and Poly I:C can yield stable, type‐1 polarized DC that produce up to 100‐fold higher levels of IL‐12p70 and can induce very high levels of melanoma‐specific CTLs as compared to standard DCs." (PMID 32663904, 2021). "However, the roleof TNF as an intrinsic factor in melanoma stem cell fate requires further studies." (PMID 34308569, 2021). "As TNFα is a key regulator of phenotypic plasticity in melanoma cells, it is tempting to speculate that the removal of TNFα or modulation of this pathway may divert melanoma cells from a dedifferentiated drug resistant state, and resensitize melanomas to therapies." (PMID 34073253, 2021). "Moreover, whether TME IL-33 alone or in combination with additional unidentified stimuli induces the high levels of ILC2 TNF-α in our melanoma model requires further exploration." (PMID 34531874, 2021). "Finally, TNFα promoted variable responses in the neural crest-like dedifferentiated melanomas." (PMID 34073253, 2021). "Following this strategy, TNF fusion proteins NGR‐TNF, targeting the neovasculature marker aminopeptidase N/CD13, and L19‐TNF, targeting an oncofetal splice variant of fibronectin, are currently in clinical development for the treatment of mesothelioma and melanoma, respectively." (PMID 31912630, 2020). "Melanoma could be divided into ”hot” and “cold” status (enrich in or lack of immune cells infiltration), and the hot status is likely to correlate with antigen processing and higher expression of interferons, TNF and chemokines pathways." (PMID 33585219, 2020). "Moreover, while no significant changes were observed in the percentage of infiltrating Tregs between B16F10 and MC38 transplanted mice bearing ICER-deficient macrophages, only in the melanoma model an enhanced IFN-γ and TNF-α production by tumor-infiltrating CTLs was observed." (PMID 33212945, 2020). "In mice with melanoma, blockade of A2B receptors reduces IL-10, monocyte chemoattractant protein 1 (MCP-1), and MDSCs in the tumor site, which is associated with increased frequency of intratumoral CD8+ T cells, elevated levels of TNF-α and IFN-γ, and delayed tumor growth." (PMID 32793192, 2020). "However, recent studies have demonstrated the efficacy of TNF-α against melanoma." (PMID 29588627, 2018). "In this context, the contribution of TNF to the anti-melanoma immune response is unknown." (PMID 29273790, 2017). "A single retrospective study found a slight increase in melanoma risk in patients treated with anti-TNF-α therapy for IBD, although no such relationship was found in larger series that have pooled patients receiving anti-TNF-α therapy for a variety of indications." (PMID 29230210, 2017). "TNF blockade (with Etanercept) or deficiency (TNF knock out) facilitates the accumulation of CD8+ Tumor-Infiltrating Lymphocytes (TILs), thereby limiting the growth of melanoma cell lines, which express Major Histocompatibility Class 1 molecules (MHCI) at high levels." (PMID 26622939, 2015). "Thus, we asked whether MITFhigh and MITFlow melanoma cell lines differ in nuclear levels of the key NF-κB subunit p65/RelA at baseline or in response to TNF-α." (PMID 26530832, 2015). "Furthermore, c-Jun engagement by TNF-α and other cytokines such as IL-1β and IL-6 is critical to trigger inflammation-induced dedifferentiation of melanoma cells and the progressive acquisition of a pro-inflammatory cell state that characterizes MITFlow/c-Junhigh melanoma cell lines and tumours." (PMID 26530832, 2015). "The relatively well documented connection between the incidence of cancer and chronic inflammation prompt us to study whether pro-inflammatory Tumor Necrosis Factor (TNF) is involved in the phenotypic switch of quiescent tumor cells into their active proliferative state in melanoma." (PMID 25223735, 2014).
melanoma (continued). "Results from a recent analysis of data from a Swedish population-based prospective cohort study (ARTIS) suggested that adults with RA who have been treated with a TNF blocker have a 50% increased relative risk of invasive melanoma relative to RA patients who have not been treated with a TNF blocker." (PMID 24225257, 2013). "Therefore, it is possible that TNFα and other molecules present in the tumor microenvironment may provide an added advantage for melanoma progression." (PMID 23965971, 2013). "The discrepancy between the ability ofFAM129B siRNAs to suppress Wnt-dependent apoptosis in melanoma and the ability of these siRNA to promote TNFα-mediated apoptosis in HeLa remains unresolved, although it does suggest that FAM129B may function in a manner that is dependent on cellular context." (PMID 24358901, 2013). "Conversely, TNF may be an important inhibitor in the melanoma microenvironment." (PMID 24225257, 2013). "However, in two melanoma patients we could detect a CD4+ specific release of TNF-α and to a lesser extend IFN-γ in response to IDOlong." (PMID 22539948, 2012). "TNF-α may be involved in anti- or protumour activities in melanoma development." (PMID 21961050, 2011). "Therefore, we can only speculate that KC maybe one of the mechanisms by which blocking TNF reduces metastasis in our in vivo melanoma model." (PMID 15026813, 2004). "Therefore, in the present study, we have investigated whether the inflammatory cytokine TNF-α acts by promoting melanoma cell migration in vitro, using this approach." (PMID 15054471, 2004). "Clinical trials of recombinant human TNF were unable to deliver therapeutic doses systemically because of toxicity, but TNF is highly effective in conjunction with chemotherapy in isolated limb perfusion for melanoma and sarcoma, where it has been shown to have selective tumour vascular effects." (PMID 12799625, 2003). "In fact, γδ T cells from patients with melanoma showed polyfunctionality with robust production of IFN-γ, TNF-α and expression of CD107a, which agrees with previous reports." (PMID 41310392, 2026). "Conversely, communication patterns of target cells indicated that incoming melanoma cell signaling was predominantly characterized by pattern 1, which including pathways such as CD99 and TNF as well as PARS, TGFb, AGRN, and MPZ." (PMID 39781353, 2025). "This study seeks to address these gaps by providing real-world longitudinal data on serum TNF-α, IL-2, and IL-10 dynamics in a cohort of patients with stage IV NSCLC and melanoma undergoing anti-PD-1 therapy with Nivolumab." (PMID 41020868, 2025). "An enzyme-linked immunosorbent assay (ELISA) further demonstrated that the cGAMP-siPDL1@GalNPs significantly triggered the highest expression levels of other immune factors, including IFN-α, IL-6, IFN-γ, and TNF-α, in the B16F10 melanoma tumors and serum." (PMID 40577452, 2025). "R.E treatment enhanced pathwaysassociated with immune activation, including upregulation of ISGssuch as IRF1, MX1, and CXCL1, as well as pro-inflammatory cytokinesincluding TNF and IL6 in melanoma cells." (PMID 41341044, 2025). "The study concluded that in tumors, such as melanoma and renal clear cell carcinoma, individuals with somatic PBRM1 mutations have increased sensitivity to treatment with PD1/PDL1 inhibitors, which might be associated with aberrant chromosomal methylation and TNF-α release." (PMID 40093909, 2025). "Despite a limited number of patients, this study provides preliminary insight into the potential predictive role of serum cytokines, TNF-α, IL-2 and IL-10 in patients diagnosed with NSCLC and melanoma undergoing anti-PD-1 immunotherapy with Nivolumab." (PMID 41020868, 2025). "Melanoma cells can switch to alternative states under specific microenvironmental stimuli, e.g., TGF-β and/or TNF-α." (PMID 41511312, 2025).
melanoma (continued). "The results demonstrated that, in the activated state, CM from Vin-treated melanoma cells similarly enhanced the expression of IFNγ, GZMB, IL-2, and TNFα in Jurkat cells." (PMID 40866941, 2025). "When co-cultured with a melanoma cell line, CSPG4-targeting CAR T cells proliferated, produced cytokines (such as IFN-γ and TNF-α), and specifically lysed CSPG4-expressing cancer cells." (PMID 39409881, 2024). "GSEA uncovered pathways known to induce phenotypic switch in melanoma, such as IL6-STAT3-, TNFα- and WNT-signaling." (PMID 39398277, 2024). "Meanwhile, increased pro‐inflammatory factors, including IL‐1β, TNF‐α, IFN‐α, and IFN‐β, were also presented in macrophages co‐cultured with irradiated melanoma cells." (PMID 38286661, 2024). "The secretion of TNF-α and IL-1α by activated TAMs triggers the production of IL-8 and VEGF-A by melanoma cells, resulting in enhanced angiogenesis and leakier vasculature." (PMID 38533720, 2024). "TAK1 blocks TNF-α-induced RIPK1 activation and apoptosis in melanoma and LPS-induced necroptosis in bone marrow-derived macrophages." (PMID 39044278, 2024). "The release of exosomal PD-L1 was increased in melanoma and glioblastoma cells, possibly due to the induction of cytokines such as IFN-α, IFN-γ, and tumor necrosis factor-α (TNF-α)." (PMID 38562933, 2024). "In mice implanted with B16-F10 melanoma cells, eosinophils inhibited tumor growth and lung metastasis, through the production of IFN-γ and TNF-α and skewing the polarization of M1 macrophages." (PMID 39126091, 2024). "In the human setting, a study reported enhanced circulating TGF-β+PD-L1+ B cells and TGF-β+:TNF-α+ B cell ratios and lower pro-inflammatory TNF-α+ B cells and IFN-γ+:IL-4+ B cell ratios as a feature of melanoma." (PMID 38533720, 2024). "The authors have identified that tumor-infiltrating B-1a cells promote melanoma growth by suppressing the production of IFN-γ and TNF-α by CD8+ T cells through an IL-10-dependent mechanism." (PMID 38629061, 2024). "Further gene signatures described to induce dedifferentiation in melanoma, such as JAK-STAT3-, TNFα- and WNT signaling, were significantly enriched in the present data set." (PMID 39398277, 2024). "In melanoma, TAM-derived TNFα mediated resistance to MAPK pathway inhibitors, and applying TNFα signaling inhibitor targeted the cancer cells and TME sensitizing the tumor to immunotherapy." (PMID 38455762, 2024). "This construct produced a significant amount of TNF and IFN-γ after co-culture with melanoma cells, but the secretion of these pro-inflammatory mediators was much lower than exhibited by the corresponding CD8+ CAR T cells." (PMID 39409881, 2024). "Then, to evaluate the impact of ceramide metabolism changes in TNF-induced melanoma cell dedifferentiation, we incubated the WM35 human primary melanoma cell line with TNF for 6, 24, 48 and 72 hours." (PMID 39136013, 2024). "Standard ILP treatment employs melphalan with tumor necrosis factor alpha (TNF-α) and has been used to treat advanced extremity sarcoma and in-transit melanoma." (PMID 38558795, 2024). "Several cytokines, including monocyte chemoattractant protein 1 (MCP-1), TNF-α, IL-6 and IL-2 have been reported to be predictive biomarkers for the response of melanoma patients to ICI treatment or for melanoma metastases." (PMID 36768978, 2023). "Intratumoral injection of Corynebacterium acnes induced Th1 cytokines such as IL‐12, tumor necrosis factor (TNF), and interferon (IFN), and inhibited the growth of melanoma cells." (PMID 36860568, 2023). "TNF‐α and IFN‐γ have been found to induce PANoptosis in cells from 13 different human cancer cell lines, including colon cancer, lung cancer, and melanoma." (PMID 38069556, 2023). "The NF-kB pathway induces cell proliferation and can be triggered when TNF-α binds to TNFR2; however, when this ligand binds to TNFR1, it can enhance apoptosis in melanoma cells." (PMID 36678596, 2023).